TIMP1 (TIMP metallopeptidase inhibitor 1)
Diseases named in the same sentence as TIMP1 in open-access papers (continued):
Sharing a sentence is not in itself a finding about the gene and the disease.
liver fibrosis (continued). "Indeed, we focused on the proteases involved in the degradation or modification of ECM (MMP-1 and TIMP-1), the products of ECM (collagen IA1) and fibrosis-related regulatory factors, such as PDGF-BB, TGF-β1, and resistin, all of whose essential roles in liver fibrosis have been established." (PMID 35715541, 2022). "In our study, it was found that treatment of rats with ICQA could significantly and dose -dependently inhibit the expression of COL1α1, TGF-β1 and TIMP-1 at both mRNA and protein levels, which indicated the potential therapeutic action of ICQA for liver fibrosis." (PMID 32425800, 2020). "Besides, the levels of TIMP-1 seemed to be firmly related with the pathological degree of liver fibrosis in patients, and suppress the expression of TIMP-1 can attenuate the progression of liver fibrosis." (PMID 32425800, 2020). "After UA treatment, this increase in the expression of type I collagen and TIMP-1 decreased, and the expression of MMP-1, an anti-fibrotic factor that promotes the degradation of extracellular matrix, was elevated, demonstrating that UV exerts a reversal effect on liver fibrosis." (PMID 32496208, 2020). "Moreover, a recent study showed that Periplaneta americana extracts alleviated CCL4-induced hepatic fibrosis in rats via the inhibition of TGF-β1, nuclear factor kappa B (NF-κB), alpha-smooth muscle actin (α-SMA), and tissue inhibitor of metalloproteinases 1 (TIMP-1)." (PMID 31885648, 2019). "The ratio of MMP9/TIMP1 and MMP13/TIMP1 showed increments in the liver after chlorophyllin treatment, indicating that administration of chlorophyllin may promote the fibrolysis and resolving liver fibrosis." (PMID 30564133, 2018). "Indeed, ELF formula includes specific compounds of the ECM (TIMP-1, PIIINP, HA), which could be more sensitive to hepatic fibrosis rearrangement occurring after HCV eradication." (PMID 27304619, 2016). "Due to the inhibition of collagenase and others enzymes involved in the turn TIMP-1 alone may not induce liver fibrosis, but it can significantly exacerbate the hepatic fibrosis." (PMID 27247426, 2016). "In human liver fibrosis, TIMP-1 expression is increased compared to that in the normal liver." (PMID 23755201, 2013). "Serum TIMP-1 levels below the cut off values could act as a surrogate marker of non-advanced liver fibrosis, thus facilitating the clinical management of patients with HCV disease when liver biopsy is unavailable or contraindicated." (PMID 21858035, 2011). "Serum levels of procollagen peptide (types III and IV), the P1 fragment of laminin, hyaluronic acid, fibrosin, TNF-aR-II and sICAM-1, tissue inhibitors of matrix metalloproteinases (TIMP)-1, and platelet-derived growth factors (PDFG)-BB may be elevated in patients with severe hepatic fibrosis." (PMID 21912706, 2011). "Moreover, TIMP1, a tissue inhibitor for matrix metalloproteinases (MMPs) is also suppressed by CHL treatment, indicating that CHL may promote MMP-mediated resolution of liver fibrosis." (PMID 34764881, 2021). "Indeed, nizatidine significantly reduced liver fibrosis measured by collagen proportionate area (CPA), α smooth muscle actin (αSMA) staining, quantitative analysis of hydroxyproline, and expression of genes mediating fibrogenesis (Acta2, Col1a1, Tgfb-1, and Timp1)." (PMID 34535664, 2021). "Furthermore, in an experimental liver fibrosis model, a dipeptidyl peptidase-4 inhibitor (DPP4-I), sitagliptin, attenuated liver fibrosis development along with the suppression of hepatic transforming growth factor (TGF)-β1, total collagen, and TIMP-1 levels in a dose-dependent manner." (PMID 30769840, 2019). "Thus, although histological signs of overt hepatic fibrosis are still absent in our model, the marked induction of TIMP-1 in the WF group suggest that with longer exposure to this WF diet fibrosis would continue unopposed, leading to progression to advanced fibrotic stages." (PMID 28294959, 2017).
liver fibrosis (continued). "Therefore, TIMP-1 might not be a determinant for promoting liver fibrosis." (PMID 37123405, 2023). "We measured MMP-2, MMP-9, and their inhibitors (TIMP-1, TIMP-2) in the CCl4-induced liver fibrosis group with/without UCB-Exo treatment." (PMID 34772443, 2021). "Although we noticed an upregulation of select acute phase response (e.g., Saa1, Saa2, and Orm2) and fibrosis genes (e.g., Col1a1 and Timp1) in livers of IXA4-treated DIO mice, IXA4 treatment did not increase liver fibrosis or the levels of multiple plasma cytokines." (PMID 35105890, 2022). "The enhanced liver fibrosis (ELF) score, which includes serum TIMP-1, PIIINP, and hyaluronic acid levels, is used to assess liver fibrosis and may be useful for distinguishing stricturing CD from non-stricturing disease." (PMID 32391365, 2020). "Recent in vitro cytology studies have shown that tanshinone IIA can inhibit TIMP-1 expression and increase MMP-1 expression in HSCs, but whether tanshinone IIA can affect liver fibrosis by regulating MMPs and TIMPs in vivo in liver tissue has not been reported in relevant animal experiments." (PMID 31915451, 2019).
breast carcinoma (189 papers, 2003 to 2026). "ERBB2 encodes the HER2-receptor, and TIMP1 is associated with breast cancer progression and metastasis." (PMID 40905789, 2025). "The utility of TIMP-1 tissue expression was also described in other types of cancers 62, including breast cancer 63, underlying novel perspectives for therapeutic approaches." (PMID 40535809, 2025). "Despite these considerations, TIMP1 overexpression has been linked to tumor proliferation, metastasis, and anti-apoptotic signaling in colon cancer and poor prognosis in breast cancer." (PMID 40427104, 2025). "For instance, it has been reported an association in breast cancer between high serum levels of TIMP1 and TIMP2 and several parameters indicative of tumoral aggressiveness and lower overall survival." (PMID 36759828, 2023). "More recently, it has been shown that TIMP-1 secreted by carcinoma-associated fibroblasts stimulates breast cancer cell-dependent secretion of TIMP-1, which in turn cooperates with CD63 and integrin β1 to promote tumor cell growth and migration." (PMID 37443843, 2023). "Panel A including MMP-9/TIMP-1 in early stages demonstrated a higher diagnostic value for breast cancer than the rest of the panels." (PMID 35222743, 2022). "An upregulation of TIMP-1 in breast cancer was associated with poor patient response to chemotherapy, due to TIMP-1 providing protection against apoptosis." (PMID 35047406, 2021). "In contrast, an increase in TIMP1 levels in tumor tissues was linked to a remarkable declined overall survival in breast cancer patients receiving standard adjuvant chemotherapy." (PMID 32420905, 2020). "Increased levels of cytosolic TIMP1 in pretreatment tumor tissue is associated with a significantly shorter OS in patients with breast cancer receiving standard adjuvant chemotherapy." (PMID 30867991, 2019). "In the present case-control study, the contributions of three TIMP-1 SNPs, rs4898, rs6609533 and rs2070584 to the risk of breast cancer was firstly evaluated in a population in Taiwan." (PMID 26872812, 2016). "In conclusion, the current study provides evidence that the C allele of TIMP-1 rs4898 contributes to an increased breast cancer risk, especially for those afflicted with TNBC." (PMID 26872812, 2016). "TIMP1 expression was increased in solid tumors, such as lung cancer, breast cancer and colorectal cancer, and was acknowledged as a risk factor of poor outcome." (PMID 26918342, 2016). "This gene has mRNA splice variants differentially associated with prognosis in primary breast cancer, nevertheless a decreased expression of TIMP-1 protein is associated with recurrence-free and overall survival (OS) in breast cancer." (PMID 26799588, 2016). "Consistent with the findings that the homozygous CC genotype of TIMP-1 rs4898 is associated with increased breast cancer risk, the allele C was 55.0% in the patient group, significantly higher than that of 45.0% in the control group (P = 2.41*10-12)." (PMID 26872812, 2016). "The allelic frequency analysis suggests that the C allele of TIMP-1 rs4898 is associated with an increased risk of breast cancer." (PMID 26872812, 2016). "The contributions of these TIMP-1 genotypes to cancer risk were examined among 1232 breast cancer patients and 1232 healthy controls, and several clinicopathologic factors were also analyzed." (PMID 26872812, 2016). "This study’s aim was to evaluate the contribution of TIMP-1 rs4898, rs6609533, and rs2070584 genotypes to the risk of breast cancer, especially the subtype of TNBC." (PMID 26872812, 2016). "Based on this finding, we assessed the association between serum levels of TIMP-1 breast cancer clinical parameters, including age (< or ≥50 years), T status, lymph node metastasis, and the ER, PR and HER2 status." (PMID 27130446, 2016). "A prognostic value of TIMP- 1 in primary breast cancer has been suggested in several studies, with high plasma or tumor tissue content of TIMP-1 being associated with poor patient outcome." (PMID 24884504, 2014).
breast carcinoma (continued). "The results presented in this manuscript suggest that TIMP-1 protein expression in cancer cells in the primary tumor evaluated by IHC is associated with improved OS for advanced breast cancer patients receiving D or GD." (PMID 24884504, 2014). "Counter intuitively, high plasma levels of TIMP-1 have also been associated with a worse outcome in breast cancer patients." (PMID 24330623, 2013). "Clinical studies using primary breast tumors, for example, have shown an association between high levels of TIMP1 mRNA and protein and poor prognosis in patients with breast cancer." (PMID 23522389, 2013). "Protein levels of TIMP-1 in tumor tissue are associated with prognosis and therapy response in patients with primary breast cancer and with response to chemotherapy." (PMID 21745383, 2011). "Finally, in breast cancer cells, iNOS-associated Akt activation necessitates TIMP1 protein nitration and TIMP1 and CD63 protein-protein interactions." (PMID 39737957, 2024). "It has been previously shown, by using a large publicly available clinical breast cancer microarray database, that TIMP-1 expression is associated with poor overall survival (OS) in TNBC patients but not in the entire BC population or in Luminal-A, Luminal-B and HER2+ BC subtypes." (PMID 37443843, 2023). "Numerous studies have demonstrated that abnormal TIMP1 expression is associated with unfavourable prognosis in various tumors, such as gastric cancer, cutaneous melanoma, papillary thyroid carcinoma and breast cancer." (PMID 37688768, 2023). "However, several studies report that high levels of TIMP-1 in the most aggressive tumors, such as colorectal cancer and breast cancer, were associated with poor outcome." (PMID 36457117, 2022). "We found that 3D structure formation and co‐culturing with breast cancer cells could promote TIMP‐1 protein secretion in hASCs; however, the underlying mechanism by which stromal cells produce TIMP‐1 has not yet been understood." (PMID 35600659, 2022). "TIMP-3 downregulation is related to cancer invasion and metastasis in various cancers; however, higher serum level of TIMP-1 is associated with lower response to therapy in breast cancer patients, and TIMP-1 has been used as a biomarker along with MMP-2 and ICAM-1 for pancreatic cancer." (PMID 32466129, 2020). "Moreover, another study reported that elevated tumor tissue TIMP1 levels were significantly associated with a poor response to paclitaxel-based chemotherapy in patients with breast cancer." (PMID 32774771, 2020). "MMP-9 and TIMP-1 have been linked to the prognosis of breast cancer." (PMID 31514476, 2019). "Moreover, in human breast cancer cells, RNAi-mediated silencing of TIMP1 induced cell cycle arrest at the G1 phase associated with AKT and NFκB signaling pathway inhibition." (PMID 28430130, 2017). "Now, in the current study, we are going to evaluate whether the genotypes of TIMP-1 are associated with an individual’s susceptibility to breast cancer, and whether these polymorphisms are associated with more invasive and aggressive TNBC." (PMID 26872812, 2016). "Recently, clinical studies have shown that the aberrant expression of TIMP1 is associated with an unfavorable prognosis in a series of tumors, such as gastric cancer, papillary thyroid carcinoma, cutaneous melanoma and breast cancer." (PMID 27644693, 2016). "TIMP-1 is often overexpressed in many malignancies and is associated with increased histological grade, lymph-node and distant metastasis and decreased survival in breast cancer." (PMID 27842517, 2016). "In addition, we analyzed the allelic frequency distributions of all three TIMP-1s, and the results showed that the C allele of TIMP-1 rs4898 contributes to an increase in breast cancer susceptibility (P = 2.41*10-12)." (PMID 26872812, 2016). "Elevated TIMP1 expression level was also associated with drug resistance in breast cancer." (PMID 25003579, 2014).
breast carcinoma (continued). "The majority of breast cancer studies on TIMP-1 and association with prognosis and response to chemotherapy have focused on patients receiving adjuvant chemotherapy, whereas only two studies have included patients with advanced breast cancer." (PMID 24884504, 2014). "It has been suggested that TIMP-1 may be produced by stromal cells and eventually become absorbed by breast cancer cells, and an association between stromal TIMP-1 expression status and progression of cancer has been reported, although not consistently." (PMID 24884504, 2014). "However, elevated TIMP-1 expression in human cancers, including breast cancer, has been associated with a decreased time to recurrence and a lower overall survival." (PMID 22339939, 2012). "It was recently shown in a prospective study that levels of TIMP-1 in plasma and serum obtained preoperatively from patients with primary breast cancer are associated with prognosis whereas plasma levels at the time of primary surgery are not correlated with tissue concentrations." (PMID 21745383, 2011). "However, a number of studies have demonstrated that the level of TIMP-1 is increased in several cancer forms, for example, colorectal and breast cancer and this increase has often been associated with a poor clinical outcome of the cancer patients." (PMID 17047657, 2006). "Thus, it is our conclusion that the CC genotype of TIMP-1 rs4898 compared to the TT wild-type genotype may increase the risk for breast cancer, especially TNBC in Taiwan, and may serve as an early detective and predictive marker." (PMID 26872812, 2016). "In addition to its inhibitory activity against MMPs, TIMP-1 promotes cell proliferation in various cell types, including breast cancer cells, and it might also be associated with anti-apoptotic activity in breast cancer." (PMID 27130446, 2016). "Thus, although several distinct signaling pathways and putative receptors have been implicated in TIMP-1 function, the mechanisms underlying the role of TIMP-1 in distinct subtypes of breast cancer remain unclear." (PMID 27130446, 2016). "However, elevated TIMP-1 expression has been associated with a poor prognosis of breast cancer." (PMID 22339939, 2012). "In breast cancer, TIMP‐1 acts as a growth factor, promoting cell proliferation and tumorigenesis, inhibiting apoptosis, and regulating ECM degradation, which can affect drug penetration." (PMID 39805002, 2025). "In female breast cancer patients undergoing neoadjuvant chemotherapy, orally administered 15 mg/kg HT determined a significant decrease in plasma levels of TIMP-1 during treatment with epirubicin and cyclophosphamide." (PMID 38540115, 2024). "High TIMP1 mRNA expression in breast cancer cells and high serum TIMP1 concentrations in patients with breast and gastric cancers are associated with poor prognosis." (PMID 36768545, 2023). "Clinical investigations have demonstrated a strong correlation between high levels of TIMP-1 expression and poor prognosis or tumor growth in various malignancies, including lung cancer, brain prostate cancer, breast cancer, colon cancer, and others." (PMID 36991043, 2023). "The analysis of TIMP-1 mRNA expression in breast cancer specimens revealed that TIMP-1 is expressed more highly in TNBC than in normal breast tissue, and the higher serum TIMP-1 levels in the malignant tissue are associated with a poor prognosis." (PMID 37443843, 2023). "Our group has previously reported the immunoreactivity pattern of TIMP‐1 protein in breast cancer cells in tissue samples." (PMID 37081824, 2023). "TIMP1 reduces drug sensitivity in breast cancer and promotes the growth of Burkitt lymphoma, colon cancer, and breast cancer cells." (PMID 36768545, 2023). "In agreement with previous findings, these cells share high TIMP-1 expression compared with the BT-474 epithelial breast cancer cell line (ER+, PR+, HER2 over-expression), with MDA-MB-231 displaying higher levels than BT-549 cells." (PMID 37443843, 2023).